RACGAP1 (Rac GTPase activating protein 1)
Diseases named in the same sentence as RACGAP1 in open-access papers (continued):
Sharing a sentence is not in itself a finding about the gene and the disease.
gallbladder cancer (4 papers, 2021 to 2024). "In gallbladder cancer, RACGAP1 sustains LIG3 protein expression through interacting with and stabilizing LIG3 to reduce apoptosis and facilitate cells growth." (PMID 38898473, 2024). "We found that five core genes (KNTC1, MCM2, CKAP2, RACGAP1, CCNB1) were highly expressed in gallbladder carcinoma samples and low in normal samples." (PMID 37480569, 2023). "Gene expression heat map showed that KNTC1, MCM2, CKAP2, RACGAP1, CCNB1 were highly expressed in gallbladder carcinoma samples." (PMID 37480569, 2023). "Rac GTPase activating protein 1 (RACGAP1) has been characterized in the pathogenesis and progression of several malignancies, however, little is known regarding its role in the development of gallbladder cancer (GBC)." (PMID 34239347, 2021).
breast tumors (3 papers, 2015 to 2025). "RACGAP1 overexpression in breast tumors is associated with a high tumor grade, HER2 positivity, and a poor prognosis." (PMID 41009526, 2025). "Through integrative analyses of transcriptomic datasets, we identified a germline-associated molecular signature, with CCNB1, CCNB2, PTTG1, RACGAP1, and UBE2C emerging as core EGT gene clusters markedly upregulated in breast tumors." (PMID 41009526, 2025). "The presence of RAC and its negative regulator RACGAP1 in the same SPNs might thus regulate growth factor signaling in P-inter breast tumors." (PMID 26257336, 2015). "The result of our experience has highlighted a significant overexpression of five CCNB1, CCNB2, PTTG1, RACGAP1, and UBE2C genes in breast tumors compared to the normal tissues (p-value < 0.05)." (PMID 41009526, 2025). "The relative gene expression analysis of seven PGC-associated genes, including CCNB1, CCNB2, FEN1, MCM4, PTTG1, RACGAP1, and UBE2C, was conducted on the samples of breast tumors compared to healthy mammary tissues." (PMID 41009526, 2025). "The average expressions of these genes in breast tumor samples compared to healthy mammary biopsies (tumor/healthy) were as follows: CCNB2 (0.483/−0.869), CCNB1 (0.262/−0.472), PTTG1 (0.398/−0.719), RACGAP1 (0.338/−0.609), and UBE2C (0.565/−1.016)." (PMID 41009526, 2025). "Breast tumor stromal cells exhibit a distinct expression profile, marked by the expression of genes such as FEN1, RACGAP1, and MCM4, which may delineate their functional identity." (PMID 41009526, 2025). "The stromal cells of breast tumors show a marked expression of genes such as PTTG1 and RACGAP1." (PMID 41009526, 2025).
colon cancer (3 papers, 2020 to 2022). "A recent paper showed that KIF23 and RACGAP1, as part of the midbody remnant formed during cytokinesis, were part of a subpopulation of EVs in colon cancer that could promote an invasive phenotype in fibroblasts." (PMID 35918030, 2022).
leukemia (3 papers, 2016 to 2024). A malignant (clonal) hematologic disorder, involving hematopoietic stem cells and characterized by the presence of primitive or atypical myeloid or lymphoid cells in the bone marrow and the blood. "Several genes from this group, such as UHRF1, MPZL1, CDK14, RACGAP1, RAB13, and others have oncogenic functions in various solid tumors, leukemias, and lymphomas either predicting poor prognosis, involved in tumor migration, metastasis, or maintenance." (PMID 38464090, 2024).
lymphoma (3 papers, 2013 to 2024). A malignant (clonal) proliferation of B- lymphocytes or T- lymphocytes which involves the lymph nodes, bone marrow and/or extranodal sites. "Median expression levels were invariably higher for AURKB, BCAT1, BIRC5, BUB1B, PBK and RACGAP1 and lower for FOSB, MAP3K1 and RIN3 by qPCR in lymphoma versus normal B cell samples in both species." (PMID 24130802, 2013).
esophageal cancer (2 papers, 2022 to 2025). A primary or metastatic malignant neoplasm involving the esophagus. "High RacGAP1 levels are correlated with poor prognosis in esophageal cancer, where RacGAP1 knockdown reduces proliferation and metastasis." (PMID 40497948, 2025). "A study on 81 esophageal carcinomas (E.C.)patients showed that RACGAP1 could play a pivotal role in E.C. development, suggesting that it could be used as an indicator of prognosis in E.C. patients." (PMID 36430577, 2022).
esophageal squamous cell carcinoma (2 papers, 2021 to 2022). Esophageal squamous cell carcinoma (ESCC) is a type of esophageal carcinoma (EC) that can affect any part of the esophagus, but is usually located in the upper or middle third. "It has been reported that E2F3, one transcription factor (TF) of E2F family proteins, regulated expression of RACGAP1 in in esophageal squamous cell carcinoma." (PMID 35958019, 2022). "Furthermore, Zhao has found that depletion of RACGAP1 could lead to mitotic catastrophe and massive cell death in esophageal squamous cell carcinoma." (PMID 34336648, 2021).
head and neck squamous cell carcinoma (2 papers, 2023). A squamous cell carcinoma that arises from any of the following anatomic sites: lip and oral cavity, nasal cavity, paranasal sinuses, pharynx, larynx, and salivary glands. "Five genes (KNTC1, MCM2, CKAP2, RACGAP1, CCNB1) were found to be associated with head and neck squamous cell carcinoma, necrosis, inflammation and hepatomegaly." (PMID 37480569, 2023). "CTD analysis showed that KNTC1, MCM2, CKAP2, RACGAP1, CCNB1 were associated with head and neck squamous cell carcinoma, necrosis, inflammation and hepatomegaly." (PMID 37480569, 2023). "RACGAP1 may regulate the downstream factors of the PI3K/AKT signaling pathway in head and neck squamous cell carcinoma." (PMID 37196108, 2023).
metastatic disease (2 papers, 2016 to 2023). "By injecting PC3 cells overexpressing RACGAP1 into the tail vein of mice, we observed the effect of overexpression of RACGAP1 on the formation of metastatic tumors in mice." (PMID 37196108, 2023). "The promotion of RACGAP1 on the biological transition of PCa and NEPC was evaluated using in vitro methods and models of transplanted tumors and metastatic tumors in vivo." (PMID 37196108, 2023).
pancreatic cancer (2 papers, 2023). "In our study, we found that RACGAP1 can be used as a telomere-related gene to accurately predict the prognosis of pancreatic cancer patients." (PMID 37391503, 2023). "We also found that high levels of DSG2, LDHA, and RACGAP1 predicted poorer overall and disease-free survival in pancreatic cancer patients, although these three genes did not all show good performance in the four validation datasets." (PMID 37391503, 2023). "Finally, we also found that protein levels of DSG2, LDHA, and RACGAP1 were upregulated in pancreatic cancer tissues compared to normal tissues by immunohistochemistry analysis." (PMID 37391503, 2023). "We established and validated a telomere gene-related prognostic signature for pancreatic cancer and confirmed the upregulation of DSG2, LDHA, and RACGAP1 expression in clinical samples, which may provide new ideas for individualized immunotherapy." (PMID 37391503, 2023). "We established and validated telomere gene-related prognostic features in pancreatic cancer and confirmed the upregulation of DSG2, LDHA, and RACGAP1 expression in clinical samples, which may provide new ideas for individualized immunotherapy targeting telomere genes." (PMID 37391503, 2023).
papillary renal cell carcinoma (2 papers, 2019 to 2023). A rare subtype of renal cell carcinoma, arising from the renal tubular epithelium and showing a papillary growth pattern, which typically manifests with hematuria, flank pain, palpable abdominal mass or nonspecific symptoms, such as fatigue, weight loss or fever. "PRC1 has revealed upper expression in other cancer tissues such as, among others, invasive cervical carcinomas, papillary renal cell carcinoma, pediatric adrenocortical tumour, while yet not being studied in depth as compared to CCNB1, ADAM10 or RACGAP1." (PMID 37438763, 2023).
acute kidney injury (1 paper, 2025). Sudden and sustained deterioration of the kidney function characterized by decreased glomerular filtration rate, increased serum creatinine or oliguria. "However, the therapeutic strategies to enhance RacGAP1 expression in vivo following acute kidney injury (AKI) remain to be explored." (PMID 41230850, 2025).
acute myeloid leukemia (1 paper, 2024). Acute myeloid leukemia (AML) is a group of neoplasms arising from precursor cells committed to the myeloid cell-line differentiation. "Our findings showed that although RACGAP1 mRNA expression was downregulated in acute myeloid leukemia, it was dramatically upregulated in most of tumors, including LUAD and lung squamous cell carcinoma (LUSC), compared to adjacent noncancerous tissues (P < 0.05)." (PMID 38622149, 2024).
adenoma (1 paper, 2013). A neoplasm arising from the epithelium. "Array data mining found that genes such as Ccnb1, Igfbp3, Nusap1, Pttg1, Racgap1, Top2a, Tpx2, which are associated with the aggressive behaviour of various human tumors, including PAs, and proto-oncogenes such as Ect2, Kit, Kras, Lyn, Ret are up-regulated in rat adenomas." (PMID 23756599, 2013). "Some genes or gene families we found up-regulated in MENX adenomas had previously been identified in human aggressive-invasive PAs, e.g., PTTG1, RACGAP1, CCNB1, CENPE, AURKB." (PMID 23756599, 2013).
cervical squamous cell carcinoma (1 paper, 2022). A squamous cell carcinoma arising from the cervical epithelium. "We found that RacGAP1 was overexpressed in cervical squamous cell carcinoma samples compared with normal cervix uteri epithelia." (PMID 35831303, 2022).
Cholecystitis (1 paper, 2021). The presence of inflammatory changes in the gallbladder. "Immunohistochemistry (IHC) was next performed in 50 samples of GBC and 50 samples of cholecystitis as controls to evaluate protein level of RACGAP1." (PMID 34239347, 2021).
COVID-19 (1 paper, 2022). A disease caused by infection with severe acute respiratory syndrome coronavirus 2. "The results of Cox analysis revealed that the RACGAP1, TCF7L2, IRF7, DMD, and JUN were significantly associated with the development of COVID-19/BRCA (p < 0.05)." (PMID 36060002, 2022). "Independent prognosis and survival analysis revealed important differential genes, including RACGAP1, TCF7L2, IRF7, DMD, and JUN, which can be used as effective biomarkers for screening and characterizing patients with BRCA and COVID-19 at all stages." (PMID 36060002, 2022).
diabetes (1 paper, 2025). "At the FAIM2 locus on chr 12q13.12, we observed known genes associated with obesity, eating patterns, and diabetes-related traits, including ASIC1, AQP2, AQP5, AQP6, RACGAP1, and AC025154.2 (AQP5-AS1) along with FAIM2." (PMID 39813287, 2025).
endometrial cancer (1 paper, 2022). Primary or metastatic malignant neoplasm involving the endometrium (mucous membrane that lines the endometrial cavity). "Based on the results of the cBioPortal web server, the endometrial cancer subtype had the highest frequency of RACGAP1 mutations, approximately 6%, where the mutation was the predominant form of genetic alterations." (PMID 36430577, 2022).
gallstones (1 paper, 2021). Solid crystalline precipitates in the biliary tract, usually formed in the gallbladder, resulting in the condition of cholelithiasis. "A higher RACGAP1 expression was linked to the larger tumor size (P = 0.015), deeper tumor invasion (P = 0.015) and the presence of gallstones (P = 0.026)." (PMID 34239347, 2021). "Our data showed that RACGAP1 expression correlates to the presence of gallstones in GBC patients, and RACGAP1 is involved in the LIG3-dependent DNA repair pathway." (PMID 34239347, 2021).
gastrointestinal stromal tumor (1 paper, 2022). "Moreover, higher RACGAP1 expression and Ki-67 index were correlated with unfavorable clinicopathological features in predicting poor outcomes of gastrointestinal stromal tumors." (PMID 36430577, 2022).
germ cell tumor (1 paper, 2024). A benign or malignant, gonadal or extragonadal neoplasm that originates from germ cells. "Rac GTPase-activating protein 1 (RACGAP1), also called MgcRACGAP, had been first detected in 1998 from human testis and germ cell tumor extracts and plays an important role in the Rho GTPase activation cycle by regulating Rho GTPase transformation and GTP hydrolysis stimulation." (PMID 38622149, 2024).
glaucoma (1 paper, 2023). Increased pressure in the eyeball due to obstruction of the outflow of aqueous humor. "Wnt signaling also activates Rac1, Racgap1, Iqgap3, and Dock2 genes in this pathway that were upregulated in three day glaucoma." (PMID 37762022, 2023).
hemangioma (1 paper, 2022). A benign vascular lesion characterized by the formation of capillary-sized or cavernous vascular channels. "By searching GSE40367 dataset, we found that RACGAP1 had higher expression in HCC with lung and lymph node metastasis compared with hemangioma and HCC without metastasis." (PMID 35958019, 2022).
invasive breast carcinoma (1 paper, 2019). A carcinoma that infiltrates the breast parenchyma. "Overexpression of DCAF13, DNMT3B, KPNA2, EXO1, FANCI, RACGAP1, and ZNF106 in invasive breast carcinoma patients showed poor survival, while overexpression of CDKN2A, SORBS1, and TP63 showed better survival." (PMID 32010179, 2019).
retinoblastoma (1 paper, 2016). A malignant tumor that originates in the nuclear layer of the retina. "Insulin growth factor 2 mRNA binding protein 1 (IGF2BP1), chromogranin A, fetuin A (ASHG), Rac GTPase-activating protein 1 and midkine that were found to be overexpressed in retinoblastoma were further confirmed by immunohistochemistry by staining 15 independent retinoblastoma tissue sections." (PMID 27799869, 2016).
serous ovarian carcinoma (1 paper, 2012). "Additionally, another gene found to be up-regulated in tumours in our dataset, Rac GTPase-activating protein 1 (RACGAP1) is an enzyme whose overexpression has also been associated with serous ovarian carcinoma." (PMID 22452920, 2012).
thyroid carcinoma (1 paper, 2019). "However, the expression levels of CCNB1 and RACGAP1 genes were significantly downregulated in at least one histological subtype of thyroid carcinoma." (PMID 30774662, 2019).
triple-negative breast carcinoma (1 paper, 2025). An invasive breast carcinoma which is negative for expression of estrogen receptor (ER), progesterone receptor (PR), and human epidermal growth factor receptor 2 (HER2). "Further functional experiments suggested that Inhibition of RACGAP1 sensitizes triple-negative breast cancer cells to ferroptosis by regulating carnitine palmitoyltransferase 1 A (CPT1A)-dependent FA metabolism." (PMID 41444950, 2025).
uterine sarcoma (1 paper, 2023). "In addition, RACGAP1 activated the STAT3-survivin signaling pathway in uterine sarcoma and hepatocellular carcinoma." (PMID 37196108, 2023).
tumor (65 papers, 2008 to 2025). "In patients with localized PCa, high RACGAP1 levels were associated with high Gleason score (p < 0.0001), lymphatic invasion (p = 0.0087), biochemical recurrence (p = 0.017) and high tumor stages (p = 0.0076)." (PMID 38898473, 2024). "RACGAP1 is also a star molecule associated with poor tumor prognosis and is involved in the development and progression of many tumors." (PMID 37391503, 2023). "Several authors reported that RacGAP1 is overexpressed in many different types of tumor tissues and associated with poor prognosis." (PMID 35831303, 2022). "RACGAP1 in the tumor was also associated with CTNBB1 expression, and inversely associated with CDKN1A gene expression." (PMID 26778597, 2016). "Moreover, increased RACGAP1 expression was significantly associated with several clinicopathologic parameters, such as the Gleason score and tumor stage levels." (PMID 37196108, 2023). "Aberrant expression of RACGAP1 caused tumorigenesis and tumor progression in multiple tumors." (PMID 35958019, 2022). "Tumor growth inhibition caused by RACGAP1 knockdown could be partially reversed by LIG3 overexpression, and we assessed the expression of γH2A.X, PAR and apoptotic signal in the subcutaneous tumors through IHC." (PMID 34239347, 2021). "For neither the IHC nor the PCR data we could confirm a significant association of RACGAP1 expression with tumor stage, tumor location, Laurén type, or H. pylori infection status." (PMID 26778597, 2016). "Similarly, there was a positive association between AURKA and RACGAP1 gene expression in the tumor‐adjacent (r = 0.425, P = 0.003) and the tumor‐distant mucosa (r = 0.699, P < 0.001)." (PMID 26778597, 2016). "H&E staining revealed that there was more tumor cells necrosis in sh-RACGAP1 group, and CPT1A overexpression weakened such necrosis caused by RACGAP1 silencing." (PMID 41444950, 2025). "Consistently, there were less Ki67 (cell proliferation marker) positive staining in tumor tissue from mice in sh-RACGAP1 group, which was enhanced after CPT1A overexpression." (PMID 41444950, 2025). "The expression levels of genes ESRP1, GRHL2, MTHFD2, RACGAP1, and SQLE, considered risk factors, were significantly up‐regulated in tumor tissues compared with normal tissues and were statistically significantly associated with a poor prognosis." (PMID 40586163, 2025). "Specifically, Ccna2, Kif2c, and Racgap1 primarily promote tumor cell proliferation and division by regulating the cell cycle and mitotic processes." (PMID 41323394, 2025). "Transcriptome data from clinical samples revealed that expression of both MAZ and RACGAP1 was increased in BRCA tumor tissue than that in normal tissue, and there was significant positive correlation between MAZ and RACGAP1." (PMID 41444950, 2025). "Recent studies have shown, RACGAP1 expression is correlated with tumor size, clinical grade, histological type, and prognosis in various tumor types." (PMID 40421085, 2025). "With regard to LC, very recently, RacGAP1 was found to be upregulated in tumor samples; Western blot analyses also indicated the involvement of the PI3K/AKT signaling pathway in the regulation of cell proliferation via RacGAP1." (PMID 40497948, 2025). "Our findings revealed that RacGAP1 was upregulated in tumor samples, independently from race and age, in both males and females, and significantly increased along the tumor stage, particularly in stage IV patients." (PMID 40497948, 2025). "Previous studies on RacGAP1 mainly focused on the role of RacGAP1 in regulating cytoplasmic division and promoting tumor progression." (PMID 41230850, 2025). "Elevated Racgap1 expression has been shown to induce abnormal cytokinesis, promoting the accumulation and expansion of aneuploid cells that accelerate malignant tumor progression." (PMID 41323394, 2025). "We utilized single-cell sequencing data to explore the tumor-related processes of RACGAP1 in LUAD and validated our findings through experimental verification." (PMID 38947404, 2024).